ADM (adrenomedullin)
Diseases named in the same sentence as ADM in open-access papers (continued):
Sharing a sentence is not in itself a finding about the gene and the disease.
encephalitis (2 papers, 2024 to 2025). An acute inflammatory process affecting the brain parenchyma. "Given that blood–brain barrier dysfunction represents a critical initiating event in neuroinflammatory disease progression, including those associated with viral encephalitis, ADM signaling may offer therapeutic potential by stabilizing endothelial tight junctions and reducing microglial activation." (PMID 41515590, 2025). "Future studies should validate these findings in larger, prospective cohorts, evaluate longitudinal dynamics, and explore the mechanistic role of ADM in neuroimmune regulation during viral encephalitis." (PMID 41515590, 2025). "Specific and effective search strategies were employed for each database utilizing the following terms: ‘MR-proADM’, ‘mid-regional proadrenomedullin’, ‘adrenomedullin’, ‘ADM’, ‘biomarkers’, ‘encephalitis’, ‘brain’, and ‘viral diseases’." (PMID 39458091, 2024). "For at least one or more of the following outcomes—encephalitis, brain injury, or lack of brain function—we considered original studies and meta-analyses reporting adrenomedullin levels in patients with neurodegenerative conditions and viral infections." (PMID 39458091, 2024).
end-stage renal disease (2 papers, 2005 to 2011). "Patients with end-stage renal failure had plasma ADM levels about fivefold greater than those of normal individuals; however, these did not change following haemodialysis." (PMID 16356231, 2005).
glomerulosclerosis (2 papers, 2010 to 2013). A hardening of the kidney glomerulus caused by scarring of the blood vessels. "After 7 weeks, kidneys are characterized by decreased function, increased proteinuria, glomerulosclerosis, increased adrenomedullin and atrial natriuretic peptide concentrations compared with salt-resistant rats." (PMID 20678234, 2010). "After 7 weeks on a high salt diet, DSS rat kidneys are characterized by decreased function, increased proteinuria, glomerulosclerosis, increased adrenomedullin and atrial natriuretic peptide concentrations compared with salt-resistant rats." (PMID 20678234, 2010). "This indicates that endogenous adrenomedullin plays an important role in protecting against oxidative stress in the kidneys via the suppression of NADPH oxidase and can prevent glomerulosclerosis." (PMID 23957015, 2013).
head and neck squamous cell carcinoma (2 papers, 2023 to 2025). A squamous cell carcinoma that arises from any of the following anatomic sites: lip and oral cavity, nasal cavity, paranasal sinuses, pharynx, larynx, and salivary glands. "In this analysis, significant upregulation of ADM expression was still observed in tumor tissues relative to adjacent normal tissues in head and neck squamous cell carcinoma (HNSC), kidney chromophobe (KICH) and kidney renal clear cell carcinoma (KIRC)." (PMID 40529377, 2025). "Targeting six immune-related genes (CXCL5, ADM, FGF9, AIMP1, STC1, and CDKN2A) in individuals diagnosed with head and neck squamous cell carcinoma has shown promising results in immunotherapy triggered by periodontal disease." (PMID 37675228, 2023).
Hyperinsulinemia (2 papers, 2022 to 2023). An increased concentration of insulin in the blood. "In an experimental study using a euglycaemic-hyperinsulinemic clamp technique, acute hyperinsulinemia was demonstrated to induce circulating ADM concentrations in obese, but not in lean individuals." (PMID 35681200, 2022).
ischemia (2 papers, 2019 to 2024). A hypoperfusion of the BLOOD through an organ or tissue caused by a PATHOLOGIC CONSTRICTION or obstruction of its BLOOD VESSELS, or an absence of BLOOD CIRCULATION. "In mouse models of ischemia with infarct induction, a knock‐out of ADM at the neuronal level results in an increase in the volume of the infarcted area and aggravation of brain damage." (PMID 38421110, 2024).
leukemia (2 papers, 2021). A malignant (clonal) hematologic disorder, involving hematopoietic stem cells and characterized by the presence of primitive or atypical myeloid or lymphoid cells in the bone marrow and the blood. "The correlation between leukemia burden and secretion of ADM reinforced the hypothesis of an autocrine secretion of ADM by leukemic blasts." (PMID 33462236, 2021). "However, it has been recently reported that CALCRL, the receptor of ADM and CGRP, is also overexpressed in LSC and its genomic ablation impaired the clonogenic capacity of AML cell lines and the frequency of chemotherapy-resistant cells able to initiate leukemia relapse in preclinical models." (PMID 34150648, 2021).
lung adenocarcinoma (2 papers, 2021 to 2025). A carcinoma that arises from the lung and is characterized by the presence of malignant glandular epithelial cells. "On the other hand, the CFAH protein has been shown to increase the oncogenic action of adrenomedullin, a peptide that promotes tumor growth in various cancer types, including lung adenocarcinoma." (PMID 35366267, 2021). "In addition, immunohistochemical (IHC) analysis was performed to further investigate the expression of ADM and its relation with PD-L1 and CD8 in lung adenocarcinoma (LUAD)." (PMID 40529377, 2025).
lung disease (2 papers, 2009 to 2020). "In contrast, one study suggested that ADM plasma levels in patients with severe lung disease are more likely caused by a systemic production than by a reduced pulmonary clearance." (PMID 19627611, 2009). "Increased ADM levels in final-stage pulmonary disease may be related to the reflection of "high demand" for these compensatory/counter-regulatory effects." (PMID 33269021, 2020).
lung squamous cell carcinoma (2 papers, 2022 to 2025). "Meanwhile, lung squamous cell carcinoma (LUSC), thyroid carcinoma (THCA), and uterine corpus endometrial carcinoma (UCEC) also presented upregulation in ADM expression compared to adjacent normal tissues." (PMID 40529377, 2025). "Although there was no clinicopathological correlation, high ADM protein expression was observed in lung squamous cell carcinoma." (PMID 35135489, 2022).
mood disorder (2 papers, 2012 to 2022). A cognitive disorder a disturbance in which the person's mood is hypothesized to be the main underlying feature. "We found a significant overlap for 6 hub genes (ADM, CITED2, IER5, NFKBIZ, SERTAD1, TNF) with similar co-expression and dysregulation patterns associated with mood disorder." (PMID 35386281, 2022).
neuroblastoma (2 papers, 2007 to 2025). Neuroblastoma (NB) is the most common solid, extracranial childhood tumor. "Peptides (angiotensin II, neuropeptide Y, neurotensin, substance P) act as oncogenic agents in neuroblastoma, whereas others (adrenomedullin, corticotropin-releasing factor, urocortin, orexin) exert anticancer effects against neuroblastoma." (PMID 40331938, 2025). "We observed that N1E-115 cells express both HIF1α and HIF2α, their common target genes VEGF and adrenomedullin as well as several neuroblastoma classical markers including neuropilin-1, neuronal-specific enolase, Id2 and chromogranin A." (PMID 17655754, 2007).
oropharynx cancer (2 papers, 2018 to 2021). A primary or metastatic malignant neoplasm that affects the oropharynx. "The ADM gene, which plays a role in carcinogenesis by regulating cellular processes including proliferation, differentiation, migration, growth, immunosuppression and hypoxia, increases lymph node metastasis risk in oral and oropharynx cancer." (PMID 33867351, 2021). "JMJD1A, H3K9me1/2 and ADM expression may be predictor markers of progression and prognosis in oral and oropharynx cancer patients, as well as putative therapeutic targets." (PMID 29590186, 2018).
orthostatic intolerance (2 papers, 2018 to 2022). "Our results are in accordance with recent studies, which reported that orthostatic intolerance (assessed using HUT + graded LBNP until presyncope) following 21-day of bedrest was associated with increased adrenomedullin levels." (PMID 30774604, 2018). "In addition to the vasodilating effects that may contribute to orthostatic intolerance, adrenomedullin has actions on fluid and electrolyte homeostasis causing natriuresis and diuresis." (PMID 35514354, 2022). "Galanin and adrenomedullin could act as biomarkers for predicting which older persons can potentially develop orthostatic intolerance." (PMID 30774604, 2018).
pancreatic adenocarcinoma (2 papers, 2016 to 2025). "As human pancreatic adenocarcinoma cell SW1990 had the lowest expression of ADM among different PDAC cell lines, we constructed the SW1990-ADM cell line which stably overexpressed ADM." (PMID 27391260, 2016).
pancreatitis (2 papers, 2023 to 2024). Inflammation of the pancreas. "This suggests the enhanced CD73 activity partially by ductal cells or ADM and most prominently by extra‐epithelial cells in wild‐type mice is allowing for an immune‐mediated rapid resolution of pancreatitis." (PMID 36468677, 2023). "Similarly, pancreatitis in caerulein-treated mice resulted in the mobilization of NLGN2 from the apical domain to the cytosol in acinar cells and ADM, and this relocalization was reversed after inflammatory injury cheased." (PMID 38413734, 2024). "In control Elast-K-Ras+/+ mice, caerulein-induced pancreatitis promoted intracellular localization of NLGN2 in acinar cells and ADM without reducing its expression level." (PMID 38413734, 2024).
periodontal disease (2 papers, 2023). "Furthermore, CXCL5, ADM, FGF9, AIMP1, STC1, and CDKN2A might have a significant impact on the development of HNSC caused by periodontal disease." (PMID 37675228, 2023).
pneumococcal pneumonia (2 papers, 2014). A febrile disease caused by STREPTOCOCCUS PNEUMONIAE. "Müller-Redetzky and colleagues propose that adrenomedullin treatment is beneficial in a mouse model of pneumococcal pneumonia and ventilator-induced lung injury." (PMID 25041977, 2014). "In the previous issue of Critical Care, the infusion of exogenous adrenomedullin is suggested to protect against increased lung endothelial permeability and end-organ dysfunction in a model of pneumococcal pneumonia in mechanically ventilated mice, possibly by stabilizing vascular endothelia." (PMID 25041977, 2014).
renal carcinoma (2 papers, 2016 to 2022). A carcinoma arising from the epithelium of the renal parenchyma or the renal pelvis. "ADM is strongly induced by hypoxia, and overexpression of ADM has been reported in several malignant conditions, including pancreatic, colorectal, and renal cancer." (PMID 35267617, 2022). "A cell viability assay showed that knockdown of ADM significantly inhibited 786-0 cell proliferation compared with the negative control group (P < 0.05), which indicated that knockdown of ADM expression had an inhibitory effect on the proliferation of renal cancer cells." (PMID 27556517, 2016).
rheumatoid arthritis (2 papers, 2021 to 2022). A chronic, systemic autoimmune disorder characterized by inflammation in the synovial membranes and articular surfaces. "For example, the increased expression of plasma and cellular adrenomedullin has been widely associated with disease activity in rheumatic diseases, including systemic sclerosis, systemic lupus erythematosus, and rheumatoid arthritis." (PMID 35720354, 2022). "We found that ADM is a stably expressed gene for rheumatoid arthritis and spondyloarthritis." (PMID 35116032, 2021). "A previous study showed that plasma and joint tissue adrenomedullin concentrations were higher in patients with rheumatoid arthritis (RA) than in those with osteoarthritis and increased with RA disease activity." (PMID 35720354, 2022).
systemic lupus erythematosus (2 papers, 2020 to 2022). An autoimmune multi-organ disease typically associated with vasculopathy and autoantibody production. "Plasma adrenomedullin levels were obviously elevated in patients with systemic lupus erythematosus (SLE) compared to those in healthy controls, and a positive correlation was found between plasma adrenomedullin levels and SLEDAI-2K, which may serve as a potential indicator of disease activity." (PMID 35720354, 2022).
Thrombocytopenia (2 papers, 2023 to 2025). A reduction in the number of circulating thrombocytes. "While dengue patients had higher SOFA scores and more severe thrombocytopenia, KFD patients had significantly higher transaminase levels and markedly elevated adrenomedullin." (PMID 41013386, 2025).
type 1 diabetes (2 papers, 2010 to 2022). "Hence, this study aimed at assessment of plasma adrenomedullin levels in type 1 diabetic children and adolescents and correlating levels with metabolic control and diabetic microangiopathy." (PMID 20181139, 2010).
viral infections (2 papers, 2024). "According to published studies, the application of adrenomedullin is not limited to determining therapeutic opportunities in bacterial and viral infections." (PMID 39458091, 2024). "Based on the available literature, there is hope for the use of adrenomedullin in detecting other viral diseases." (PMID 39458091, 2024). "This review highlights the growing importance of adrenomedullin as a biomarker in viral diseases and the need for further functional studies to understand the underlying mechanisms involved." (PMID 39458091, 2024). "Adrenomedullin has emerged as a promising biomarker in the field of viral diseases." (PMID 39458091, 2024). "Furthermore, adrenomedullin has been shown to be elevated in various viral infections, suggesting its role in immune response modulation." (PMID 39458091, 2024).
age-related macular degeneration (1 paper, 2013). Age-related loss of vision in the central portion of the retina (macula), secondary to retinal degeneration. "Suppression of ADM signaling might be a valuable alternative treatment for CNV associated with age-related macular degeneration." (PMID 23520487, 2013).
Alzheimer disease (1 paper, 2022). A progressive, neurodegenerative disease characterized by loss of function and death of nerve cells in several areas of the brain leading to loss of cognitive function such as memory and language. "NEP inactivates a wide range of peptide substrates including enkephalins, neurokinin A, substance P, bradykinin, endothelins, somatostatin, adrenomedullin, bombesin‐like peptides, glucagon, thymopentin as well as the amyloid‐β (Aβ) which accumulates in Alzheimer's disease (AD)." (PMID 35212467, 2022).
anxiety disorder (1 paper, 2018). A category of psychiatric disorders which are characterized by anxious feelings or fear often accompanied by physical symptoms associated with anxiety. "Conversely, another study found reduced levels of ADM in patients with anxiety disorder." (PMID 30020987, 2018).
atopic dermatitis (1 paper, 2022). "In addition, activation of MRGPRX2 by the neuropeptide substance P (SP) and the pro-adrenomedullin peptide (PAMP-12) is associated with a variety of cutaneous conditions such as neurogenic inflammation, pain, atopic dermatitis, urticaria, and itch." (PMID 36275683, 2022).
autoimmune disease (1 paper, 2025). A disorder resulting from loss of function or tissue destruction of an organ or multiple organs, arising from humoral or cellular immune responses of the individual to their own tissue constituents. "Adrenomedullin (ADM), a multifunctional peptide, has been implicated in various inflammatory and autoimmune diseases." (PMID 40529377, 2025).
Bartter syndrome (1 paper, 2022). "ADM levels in childhood have been studied in Bartter syndrome, minimal change nephrotic syndrome, primary nocturnal enuresis, detrusor instability, and VUR." (PMID 36010070, 2022). "The same author studied the role of NO and ADM in Bartter syndrome, in which patients are known to have a lower vascular reactivity." (PMID 36010070, 2022). "It was found that urinary nitrite and ADM excretion was lower in Bartter syndrome patients, suggesting a potential role of these two molecules in the reduced vascular response seen in the disease." (PMID 36010070, 2022).
bladder carcinoma (1 paper, 2020). "TRPV2 activation was also shown to promote bladder cancer cell metastasis via either matrix metalloproteinase-2- (MMP-2-) or adrenomedullin-dependent mechanisms in the human bladder carcinoma cell line T24/83." (PMID 33376561, 2020).
bladder tumour (1 paper, 2025). "We found that seven of these genes, IGFBP3, VEGF, CCNG2, NDRG1, PFKFB3, ADM and SLC2A1, were also upregulated in MIBC and/or NMIBC in our study, suggesting parallel hypoxia-induced expression changes with primary bladder tumour tissue." (PMID 40867253, 2025).
cardiopulmonary disease (1 paper, 2022). "Higher ADM levels in the setting of cardiopulmonary disease could reflect protective measures to limit the production of pro-inflammatory cytokines as well as help repair endothelial cells." (PMID 35390066, 2022).
congenital heart disease (1 paper, 2022). A heart disease that is present at birth. "ADM is significantly elevated in patients with PH (primary and related to congenital heart disease) when compared to those without PH, and a significantly increased uptake of plasma ADM in pulmonary circulation has been demonstrated in these patients." (PMID 36010070, 2022).
Cryptococcal meningitis (1 paper, 2022). Meningeal inflammation produced by cryptococcus neoformans, an encapsulated yeast that tends to infect individuals with acquired immunodeficiency syndrome and other immunocompromised states. "In Cryptococcal meningitis (CM), circ-0001806 acts as a sponge of miRNA-126, positively regulates the level of Adrenomedullin (ADM), and reduces apoptosis and G1/S arrest in T cells." (PMID 35806027, 2022).
dengue (1 paper, 2025). "In children with severe dengue, adrenomedullin levels were significantly higher than in healthy controls and correlated with markers of plasma leakage." (PMID 41013386, 2025).
Dengue hemorrhagic fever (1 paper, 2024). A serious condition caused by Dengue virus infection. "Notably, elevated ADM levels have been observed not only in dengue hemorrhagic fever (DHF) but also in dengue shock syndrome (DSS)." (PMID 39458091, 2024).
diabetic nephropathy (1 paper, 2013). "This is supported by evidence showing that the genetic predisposition to develop diabetic nephropathy is associated with the microsatellite DNA polymorphism of the adrenomedullin gene." (PMID 23957015, 2013). "Although the organoprotective effects of adrenomedullin have been demonstrated in various cardiovascular diseases, the mechanisms underlying its renoprotection in diabetic nephropathy are still unclear." (PMID 23957015, 2013). "The activation of an endogenous adrenomedullin may therefore be a novel therapeutic approach for effective treating of diabetic nephropathy." (PMID 23957015, 2013). "Therefore, we believe that endogenous adrenomedullin counteracts the pathogenesis of diabetic nephropathy possibly through an antioxidative stress action via the suppression of NADPH oxidase and the renin-angiotensin system." (PMID 23957015, 2013). "Adrenomedullin has been demonstrated to possess an antioxidant action; however, the relationship between NADPH oxidase and adrenomedullin in the kidneys of diabetic nephropathy remains to be elucidated." (PMID 23957015, 2013). "However, the role of adrenomedullin in diabetic nephropathy has not been clearly elucidated." (PMID 23957015, 2013).
emphysema (1 paper, 2023). "Adrenomedullin and myosin light chain kinase family member 4 (MYLK4) act against emphysema." (PMID 38203236, 2023).
fibrosarcoma (1 paper, 2018). A malignant mesenchymal fibroblastic neoplasm affecting the soft tissue and bone. "In Nox4 knockout mice with fibrosarcoma, vessel density analysis showed a significant reduction in tumor vascularization, leading to the attenuation of hypoxia-inducible factor 1-alpha, vascular endothelial growth factor, glucose transporter 1 and adrenomedullin." (PMID 30513726, 2018).